CD163 (CD163 molecule)
Diseases named in the same sentence as CD163 in open-access papers (continued):
Sharing a sentence is not in itself a finding about the gene and the disease.
liver fibrosis (33 papers, 2016 to 2025). "LECT2 expression in serum and liver macrophages was associated with increased TGF-beta 1 secretion by liver CD163 (+) M2 macrophages and liver fibrosis." (PMID 40270513, 2025). "Meanwhile, western blot analysis results showed that CD206 and CD163, both of which are associated with M2 macrophages, were significantly increased in the β1-AA-induced hepatic fibrosis model, overlapping with the phase of hepatic fibrosis." (PMID 35983976, 2022). "The results revealed that LECT2 and CD163 + macrophages have a mutually promoting role in BA liver fibrosis." (PMID 35928681, 2022). "To determine the changes in macrophage phenotype after treatment of exosomes, we use immunofluorescence to label CD68 and CD163 in paraffin sections of liver fibrosis." (PMID 36183106, 2022). "To examine the relationship between hepatic M2 macrophages and liver fibrosis stages, we first compared the expression of CD163 (mainly expressed on M2 macrophages) in different stages of hepatic fibrosis among patients." (PMID 33614685, 2021). "As regards hepatic fibrosis, our results showed that cases of post-hepatitis fibrosis of high scores (F3 and F4) showed higher degrees of IL-4, IL-17, and CD163 expression, compared to low scores of hepatic fibrosis (F1 and F2)." (PMID 33906302, 2021). "We then administered the preparations to the STAMTM mouse model to test if the preparation could exacerbate NASH and liver fibrosis with a concomitant increase in CD163+ M2 macrophage and a decrease in IL−6." (PMID 37175803, 2023). "In addition, western blot analysis showed that the M2 macrophage markers, CD206 and CD163, were upregulated at the 8th week, whereas the M1 macrophage marker, TNFα, was upregulated at the 16th week of the β1-AA-induced hepatic fibrosis." (PMID 35983976, 2022). "Herein, we observed that the densities of peritumoral infiltrated CD163+ cells are positively correlated with expression of CD68+ macrophages, demonstrating that the development of liver fibrosis should be closely linked to the advancement and poor prognosis of HCC." (PMID 36142683, 2022). "So, in what way does LECT2 interact with CD163+ macrophages in the process of BA liver fibrosis?" (PMID 35928681, 2022). "Furthermore, hepatic fibrosis, scored as the sum of pericellular and perivenular fibrosis as well as glycogen deposition, was significantly reduced only in the anti-CD163-dexamethasone group." (PMID 28344991, 2017). "The activation of KCs during liver fibrosis and inflammation upregulates CD163 expression and promotes the release of sCD163." (PMID 40099185, 2025). "In conclusion, we found increased expression of hepatic CD163 and CCL2 in patients with HBV-related fibrosis; the expression increased dramatically with further progression of liver fibrosis." (PMID 33614685, 2021). "Serum levels of CD163, a marker of liver macrophage subpopulation, also correlated with HCV-related liver fibrosis and was proposed as a novel marker for assessing the degree of liver fibrosis in HCV-infected patients." (PMID 34065048, 2021). "Although CD163+ M2 macrophages were increased in the liver, and serum IL−6 levels were reduced in MSC−sEV treated animals, our data suggests that MSC−sEV treatment was efficacious in reducing liver fibrosis in a mouse model of NASH despite an increase in pro−fibrotic M2 macrophage polarization." (PMID 37175803, 2023). "However, the link between hepatic CD163+ macrophages accumulation and liver fibrosis progression remain elusive, and experimental evidence for the reasons why CD163 upregulation during liver fibrosis is still lacking." (PMID 33614685, 2021).
Insulin resistance (30 papers, 2011 to 2025). Increased resistance towards insulin, that is, diminished effectiveness of insulin in reducing blood glucose levels. "Although our univariate analysis findings were also compatible with those studies, the association between sCD163 and insulin resistance is rather weak than monocyte CD163 in patients with type 2 diabetes." (PMID 29445750, 2017). "Monocyte surface CD163 expression levels were more significantly associated with insulin resistance than sCD163 in patients with type 2 diabetes, suggesting a novel pathophysiological role of CD163." (PMID 29445750, 2017). "First, our study is of cross-sectional design and is therefore not able to draw conclusive causal relationship between monocyte CD163 and insulin resistance." (PMID 29445750, 2017). "Monocyte/macrophage-specific soluble CD163 (sCD163) concentration is associated with insulin resistance and increases with deteriorating glycemic control independently of BMI." (PMID 25624106, 2015). "The background for the link between CD163 and insulin resistance is yet to be understood despite a clear association." (PMID 24741586, 2014). "Serum levels of soluble TNF-like weak inducer of apoptosis (sTWEAK) and its scavenger receptor CD163 (sCD163) have been linked to insulin resistance." (PMID 24978196, 2014). "Monocyte surface CD163 expression levels were significantly associated with insulin resistance in type 2 diabetes patients, which showed the pathophysiological role of monocyte CD163 in the development of insulin resistance." (PMID 30533447, 2018). "Soluble CD163 (sCD163) was shown to be associated with insulin resistance in humans and may be a more reliable measure of T2D than TNF-α; sCD163 secreted by macrophages should be examined further in the dolphin as well." (PMID 24101915, 2013). "• Promotes energy consumption by stimulating the hypothalamus. • Correlation with high TNFα levels and insulin resistance. • Chemotaxis and monocyte infiltration in adipose tissue by the expression of CD11b and CD163." (PMID 35422689, 2022). "The CD36, GLUL, MYH11, CD163, and COL4A2 genes were closely associated with weight loss, while the ACACB gene was closely related to insulin resistance." (PMID 34085602, 2021). "These evidences evoke us of a concept that monocyte CD163 is a potential protective marker for insulin resistance." (PMID 29445750, 2017). "Possibly, the produced IL-10, but also CD163 and arginase in adipose tissue macrophages only play a paracrine role, thereby preventing adipose tissue injury from excess inflammation and insulin resistance." (PMID 22018099, 2011). "The mechanisms underlying the role of monocyte CD163 in insulin resistance were not determined from our clinical study." (PMID 29445750, 2017). "Therefore, it is necessary to elucidate the pathophysiological role and clinical implication of monocyte CD163 for insulin resistance." (PMID 29445750, 2017). "Our results indicate that CD163, both in terms of the gene expression and the soluble part of the receptor, may be of importance in regard to insulin resistance." (PMID 24741586, 2014). "To date, the association between monocyte CD163 and insulin resistance is not well studied." (PMID 29445750, 2017). "Indeed, monocytes with low CD163 expression identified in our study can be considered to be a precursor of M1 macrophages located in local adipose tissue, which play an important role for insulin resistance." (PMID 29445750, 2017). "In conclusion, the present study demonstrated the closer association between surface monocyte CD163-expressing monocytes from the peripheral blood, rather than serum sCD163 levels, and insulin resistance, independent of known clinical factors in patients with type 2 diabetes." (PMID 29445750, 2017). "Furthermore, animal models with monocyte specific overexpression or knockdown of CD163, if made in the future, might elucidate basic mechanisms between monocyte CD163 and insulin resistance." (PMID 29445750, 2017).
Insulin resistance (continued). "This may explain why sCD163 is a less sensitive marker for insulin resistance than monocyte CD163." (PMID 29445750, 2017). "Anthropometric parameters, Homeostatic Model Assessment for Insulin Resistance (HOMA-IR), lipid profile, and concentrations of TWEAK and CD163 were determined." (PMID 35898446, 2022). "Therefore, our data suggests that measurements of monocyte CD163, rather than sCD163, serve as a better surrogate marker for pathophysiological impact in insulin resistance for patients with type 2 diabetes." (PMID 29445750, 2017).
osteosarcoma (29 papers, 2015 to 2026). A usually aggressive malignant bone-forming mesenchymal neoplasm, predominantly affecting adolescents and young adults. "TAMs expressing CD14 or CD163 are associated with improved overall survival and metastasis-free survival in multiple osteosarcoma cohorts." (PMID 39359731, 2024). "Consistently, CD163+ M2 tumor-associated macrophages inhibits the infiltration of T lymphocytes in osteosarcoma, causing osteosarcoma cells to escape the killing of the immune system." (PMID 33868316, 2021). "Our results further emphasized that CD163+EPOR+ TAMs are associated with the progression of osteosarcoma lung metastasis." (PMID 32908942, 2020). "Our data demonstrated that the increased percentage of CD163+EPOR+ TAMs was associated with a poor prognosis for osteosarcoma lung metastasis patients." (PMID 32908942, 2020). "We have characterized TAMs expressing EPOR and CD163+EPOR+ macrophages as TAMs in osteosarcoma lung metastasis patients, which are highly associated with tumor aggressiveness." (PMID 32908942, 2020). "The number of TAMs in tissue from sarcoma patients indicates that M2-like macrophages expressing CD163 are correlated with poor prognosis in patients with leiomyosarcoma, myxoid liposarcoma, and osteosarcoma." (PMID 36900335, 2023). "The same results were obtained in osteosarcoma, where CD163+ macrophages were significantly correlated with CD146+ and macrophage activation factor (cMAF)+ macrophages and were associated with a higher OS rate." (PMID 37958467, 2023). "Opposite results were obtained in the preclinical models of osteosarcoma, in which CD163+ M2 macrophages were correlated with tumor growth, vascularization, and metastasis." (PMID 37958467, 2023). "Then, we showed that CD163+EPOR+ macrophages in osteosarcoma lung metastasis specimens are TAMs that have developed a distinctive effect in supporting the progression of osteosarcoma lung metastasis." (PMID 32908942, 2020). "To further analyze the characterization of CD163+EPOR+ TAMs in osteosarcomas, we determined M2 cytokine expression of sorted CD163+EPOR+ TAMs in osteosarcoma and para-osteosarcoma tissues." (PMID 32908942, 2020). "Little is known, however, about the expression of EPOR on TAMs and the identity of CD163+EPOR+ TAMs in osteosarcoma lung metastasis has yet to be fully explored." (PMID 32908942, 2020). "In conclusion, we have identified and characterized CD163+EPOR+ macrophages as TAMs in osteosarcoma lung metastasis patients." (PMID 32908942, 2020). "We also showed that CD163+EPOR+ TAMs were increased 2.5-fold in human osteosarcoma lung metastasis samples." (PMID 32908942, 2020). "We further examined the clinical prognosis of the percentage of CD163+EPOR+ TAMs in the 106 patients with osteosarcoma lung metastases." (PMID 32908942, 2020). "Collectively, our data implied that the percentage of CD163+EPOR+ TAMs was a potential significant prognostic factor in patients with osteosarcomas." (PMID 32908942, 2020). "Univariate analyses proposed that a ≥2.5-fold increase in the percentage of CD163+EPOR+ TAMs was significantly associated with decreased mDFS and mOS in osteosarcoma lung metastasis patients." (PMID 32908942, 2020). "A subpopulation of CD163+ macrophages expresses EPOR in human osteosarcoma lung metastasis specimens." (PMID 32908942, 2020). "This study showed that >2.5-fold percentage of CD163+EPOR+ TAMs in osteosarcoma tissues had a significant impact on osteosarcoma prognosis." (PMID 32908942, 2020). "In conclusion, our study suggests that TAMs in osteosarcoma lung metastasis samples express EPOR and CD163+EPOR+ macrophages are true TAMs that can promote the progression of osteosarcoma lung metastasis under EPO stimulation." (PMID 32908942, 2020). "In order to clarify the role of macrophages in osteosarcoma, future studies should correlate the presence of CD68+/CD80+ M1 and CD68+/CD163+ M2 macrophages to osteosarcoma survival." (PMID 27456063, 2016).
osteosarcoma (continued). "In human osteosarcoma lung metastasis specimens, a subpopulation of CD163+ macrophages was found to express erythropoietin receptor (EPOR), CD206, CD163, and PD1, which are known to play significant roles in TAMs immune suppressive and tumor-promoting functions." (PMID 38927907, 2024). "However, a recent study also suggested that the presence of CD163-positive M2-polarized macrophages is essential for the inhibition of osteosarcoma progression, which is in contrast to what is observed in other solid tumors." (PMID 35991561, 2022). "CD163+EPOR+ macrophages were shown to be true TAMs in osteosarcoma lung metastasis specimens." (PMID 32908942, 2020). "Improving anemia and targeting CD163+EPOR+ TAMs may serve as potential therapeutic interventions in osteosarcoma lung metastasis." (PMID 32908942, 2020). "Our findings show that M2 cytokines were highly expressed by CD163+EPOR+ TAMs in osteosarcoma lung metastasis tissues suggested the possibility that CD163+EPOR+ TAMs enhanced the progression of osteosarcoma lung metastasis patients by secreting many different M2 cytokines." (PMID 32908942, 2020). "We quantified the relative percentage of CD163+EPOR+ TAMs in osteosarcoma lung metastasis tissues." (PMID 32908942, 2020). "Having shown that the percentage of CD163+EPOR+ macrophages was increased in osteosarcoma lung metastasis specimens, we examined the expression profiles of these molecules on CD163+EPOR+ and CD163+EPOR− macrophages in osteosarcoma lung metastasis tissues by flow cytometry." (PMID 32908942, 2020). "However, a recent study based on the most important cohort of osteosarcoma patients from the OS2006 clinical trial has demonstrated that the presence of CD163+ M2-polarized macrophages is crucial for the inhibition of osteosarcoma progression." (PMID 31370265, 2019). "Although the prognostic relevance of CD68+ and CD163+ macrophage infiltration in osteosarcoma was not described, lower SIRPα levels were associated with a worse overall survival among non-translocation sarcomas, and CD47 expression turned out to be a poor prognostic factor in osteosarcomas." (PMID 33802565, 2021). "Thus, we speculated that combined analyses of anemia and the percentage of CD163+EPOR+ TAMs may better predict the prognosis of osteosarcoma lung metastasis patients." (PMID 32908942, 2020). "In a comparative study involving 20 samples each of Ewing sarcoma and osteosarcoma, the median percentage of CD163+/CD68+ M2‐polarized TAMs was approximately 3% of the tumor area in Ewing sarcoma, notably lower than the ∼15% observed in osteosarcoma." (PMID 41357670, 2025). "On the other hand, in osteosarcoma, CD14+HLA-DR+ M1 macrophages and CD14+CD163+ M2 macrophages were observed." (PMID 37958467, 2023). "Firstly, we referred to two data sets, GSE12865 and GSE14395, and showed that there were high expression levels of four classical M2 macrophages markers, CD163, CCR2, and MRC1, in human osteosarcoma tissue samples." (PMID 35889217, 2022). "Consistent with the RNA-seq prediction and the previous findings in a subset of TARGET osteosarcoma cohort, there were robust infiltrating T cells (markers CD3, CD8) and M2 macrophages (CD163), with moderate PD-L1 expression in these osteosarcoma samples." (PMID 34818552, 2021). "We first analyzed the expression profiles of CD163+EPOR+ TAMs in osteosarcoma and para-osteosarcoma tissues." (PMID 32908942, 2020). "CD163+EPOR+TAMs increase 2.5 times in human osteosarcoma lung metastasis tissues; CD206, CD163, and PD1, which are known to have a significant role in TAM function had high expression in CD163+EPOR+ TAMs compared with CD163+EPOR− TAMs." (PMID 32908942, 2020). "Our results indicated that the relative mean fluorescence (RMFI) of CD163, CD206, and PD1 was increased in osteosarcoma tissues compared with para-osteosarcoma tissues, while, the expression of CD14 and CD16 did not change." (PMID 32908942, 2020).
osteosarcoma (continued). "Taken together, our data clearly suggest that combined analyses of anemia and the percentage of CD163+EPOR+ TAMs were a better predictor for recurrence and survival in osteosarcoma lung metastasis patients than analyzing individual factors." (PMID 32908942, 2020). "CD47-expressing osteosarcoma specimens showed significantly (p < 0.001) higher levels of TAM markers CD68 and CD163 compared to osteomas and normal bones." (PMID 30674867, 2019). "Clinically, our results reinforce the paradigm that M1-biased macrophage signatures are associated with favorable prognosis, whereas high burdens of M2/TAM subsets (e.g. CD163+ or EPOR+CD163+ TAMs) predict aggressive disease and metastatic potential in osteosarcoma patients." (PMID 41346635, 2025). "The vascularendothelial cell population in the osteosarcoma lesion tissues exhibiteda PECAM1­(+), CDH5­(+) phenotype, whereas the macrophage populationwas predominantly of the M2 type, expressing CD163­(+) and MRC1­(+),consistent with the characteristics of the tumor immune microenvironment." (PMID 40834268, 2025). "Further characterization of four DC subclusters based on CD14/CD163, cDC1, cDC2, and CCR7 marker positivity demonstrates a higher number of cDC2 found in the TME of metastatic lung lesions than in primary and recurrent osteosarcoma." (PMID 39359731, 2024). "Furthermore, CD163+EPOR+ TAMs had higher M2 marker and cytokine expression in osteosarcoma tissues compared with para-osteosarcoma tissues." (PMID 32908942, 2020). "In the future, RNA-seq analyses of CD163+EPOR+ TAMs may help us to better understand of this subset of TAMs, and targeting TAM therapy may be a potential therapeutic intervention in osteosarcoma lung metastasis patients." (PMID 32908942, 2020). "For instance, Gomez and his colleagues proposed a systematic analysis of CD68, CD163, CD8, PD1 and PDL-1 expression performed in osteosarcoma biopsies to stratify patients regarding their respective TME and suggested a therapeutic strategy targeting macrophages and other immunological factors." (PMID 33363016, 2020). "The GDC data portal revealed elevated levels of M1 macrophage markers (CD163 and CD206) without any M2 macrophage markers in osteosarcoma samples." (PMID 39247831, 2024). "A high number of CD14+/HLA-DRα+ macrophages was also associated with a better OS, vascularity and a better response to chemotherapy treatment in osteosarcoma; however, the M2 phenotype of CD14+/CD163+ macrophages was not related to OS." (PMID 37958467, 2023).